BRD4 (bromodomain containing 4)
Diseases named in the same sentence as BRD4 in open-access papers (continued):
Sharing a sentence is not in itself a finding about the gene and the disease.
tumor (continued). "Moreover, the interaction with the deubiquitinating enzyme UCHL3 results in the stabilization of BRD4 and a reduced binding capacity to BET inhibitors, thereby leading to tumor cell resistance." (PMID 39838405, 2025). "One promising strategy involves the use of bromodomain-containing protein 4 (BRD4) inhibitors or bromodomain and extraterminal domain inhibitors (BETis) to downregulate NFIC expression, potentially inhibiting tumor progression and increasing the efficacy of existing treatments." (PMID 41194225, 2025). "Inhibition of BRD4 by JQ1 disrupts its interaction with acetylated histones, blocking the recruitment of transcriptional machinery and subsequently reducing the expression of genes critical for tumor growth." (PMID 41323280, 2025). "Similarly, bromodomain-containing protein 4 (BRD4) and histone deacetylase (HDAC) inhibitors were reported to trigger differentiation and tumor regression in xenograft models or patients." (PMID 39859209, 2025). "The inhibition of BRD4 and SMAD3 through BETi or genomic editing can be valuable therapeutic strategies to exploit the anti-tumor potential of NK cells in adoptive NK/CAR-NK cell therapies or, alternatively, to rescue/enhance autologous NK activity in TME of NSCLC patients." (PMID 38519469, 2024). "In addition, bromodomain-containing 4 (BRD4) inhibition was shown to prevent cell proliferation and epithelial–mesenchymal transition (EMT) and play an anti-tumour role in RCC by activating the NF-κB–NLRP3–caspase-1 pyroptosis signalling pathway." (PMID 38103146, 2024). "From the analysis of in vivo data, it is possible to infer that HBL‐4 degrader had great antitumor effects in MV4‐11 tumor xenograft model, through the degradation of PLK1 and BRD4, in a well‐tolerated way, surpassing the effects observed with the use of TLM inhibitor." (PMID 38845697, 2024). "In addition to these 5 cases, we describe 4 additional unpublished new cases of CNS tumors with BRD4::LEUTX fusions, thereby expanding the limited characterization available for this tumor type to date." (PMID 38500181, 2024). "To examine the expression profile of BRD4 in HPV16-positive HNSCC, we evaluated the expression of BET genes using the publicly available, curated TCGA dataset, UALCAN, which included 44 normal (adjacent tissue to the tumor) and 41 HPV-positive HNSCC patients." (PMID 39301555, 2024). "To examine whether the REV-ERBα, FOXA1, and BRD4 regulatory axis plays a function in vivo in control of tumorigenic gene programs, we first performed FOXA1 and REV-ERBα ChIP-seq analysis with a PDX tumor model." (PMID 39383000, 2024). "For example, JQ1, a tert-butyl synthetic precursor of OTX015, is a prototype BET inhibitor (BETi), which competitively binds to the bromodomain and displaces BRD4 from super-enhancers for the MYC oncogene thus impeding tumor cell growth in various malignancies, including MM." (PMID 39160158, 2024). "Earlier, we reported that HOXB13 is an epigenetic target of BRD4 in CRPCs, and suppression of HOXB13 expression by the BET inhibitors JQ1 or MA4-class of compounds induces apoptosis and significantly inhibits PC xenograft tumor growth." (PMID 38730575, 2024). "In addition, a combination of BRD4 and PLK1 inhibitors showed synergistic anti-tumour effects in paediatric tumour models including RMS that is associated with MYCN-driven gene expression." (PMID 38191874, 2024). "Flow cytometry examination showed that JTP+Laser instead of JP+Laser highly efficiently inhibits IFN-γ-inducible PD-L1 expression on the surface of the tumor cell membrane as free JQ1 in both 4T1 and Panc02 tumor cells in vitro, validating PDT-activatable BRD4 inhibition profile of JTP prodrug." (PMID 37328484, 2023). "In pediatric neuroblastoma xenograft models, 99 can slow tumor growth accompanied by reduced c-MYC, loss of BRD4 and increased HEXIM1, with no significant toxicity." (PMID 37142850, 2023).
tumor (continued). "Overall, the expression of BRD4, one of BET genes, may play an important role in tumor development by participating in immune response." (PMID 36711038, 2023). "Furthermore, BRD4 is capable of tethering to collagen‐ and calcium‐binding epidermal growth factor domain‐containing protein 1 (CCBE1) enhancers, a known booster of tumour lymphangiogenesis." (PMID 37994501, 2023). "BRD4 inhibitor expanded CD4+ and CD8+ T cell populations in the tumor microenvironment." (PMID 37685868, 2023). "Consistent with the analysis of TCGA data, BRD4 expression was significantly higher in tumor group than normal group." (PMID 36711038, 2023). "In Case 1, the NUTM1 break-apart signal was observed in 84% of tumor cells, whereas the tumor was negative for BRD4::NUTM1, SS18, and EWSR1 rearrangements." (PMID 38239638, 2023). "Overall, the expression of BRD4, one of the BRD family genes, may play an important role in tumor development." (PMID 36711038, 2023). "Bromodomain-containing protein 4 (BRD4) is a member of the Bromo- and Extra-Terminal domain (BET) family that is upregulated in tumor cells and regulates gene expression by recruiting various transcription factors by interacting with the acetylated lysine residues of histone tails on chromatins." (PMID 37685868, 2023). "Although we did not observe significant effects on immune cells in tumor-draining lymph nodes upon RT or BRD4 inhibition, we noticed a remarkable increase in splenic T cells." (PMID 37685868, 2023). "Small molecule compound BRD4 BD1 and BD2 bromodomain inhibitors block BRD4 binding to super-enhancers, suppress oncogene transcription and expression, reduce cancer cell proliferation and survival, and repress tumor progression in a variety of cancer types." (PMID 38135679, 2023). "The hydrophobic l‐phenylalanine‐poly(ester amide) nanoparticles (JQ1/THZ1@8P4 NPs) could be loaded with JQ1 (a BRD4 inhibitor) and THZ1 (a CDK7 inhibitor) to target tumor sites." (PMID 36599655, 2023). "Mechanistically, exosomal circLPAR1 was internalized by CRC cells, and it suppressed tumor growth, likely because exosomal circLPAR1 directly bound with eIF3h specifically suppressed the METTL3-eIF3h interaction, decreasing the translation of oncogene BRD4." (PMID 35164758, 2022). "For example, the BRD4 inhibitor JQ1, in which BRD4 is a member of the BET family (Bromodomain and Extra Terminal domain), has shown therapeutic potential in patient-derived xenografts by impairing tumour progression and sensitizing tumours to PARP inhibitors." (PMID 35326669, 2022). "TUNEL staining of the tumour sections revealed notable apoptosis of the tumour cells from the mice in the PED + N3@PGDA7 + PDT group, suggesting that the combination of PDT and BRD4 degradation with the bioorthogonal NPs cumulatively induced apoptosis of the tumour cells in vivo." (PMID 35882867, 2022). "Although BRD4 is required to maintain mitochondrial function and aerobic metabolism, tumour cells gradually evolve to survive independent of mitochondria due to chronic lack of nutrient and oxygen supply." (PMID 36309482, 2022). "Based on this cohort, we compared the translational levels of BRD4 between tumor and non-tumor tissues." (PMID 36352160, 2022). "For example, a study implicating ERK5 in promoting cancer stem cell-like properties and tumour-sphere growth in colorectal cancer relied heavily on the use of XMD8-92 making it unclear if the study is reporting ERK5 dependency, BRD4 dependency or both." (PMID 35903549, 2022). "On the other hand, BRD4 mRNA and protein levels were decreased in SKI-349-treated tumor tissues." (PMID 35831279, 2022). "The BRD4-NUT oncoprotein can bind and activate histone acetyltransferase, which leads to the acetylation of chromatin and creates a feed-forward mechanism leading to neoplasia." (PMID 35832518, 2022). "In GC, the expression of BRD4 is significantly higher in tumor tissues than in adjacent non-tumor tissues." (PMID 36352160, 2022).
tumor (continued). "Moreover, JQ1 and VS-6063 (an inhibitor of the focal adhesion kinase (FAK))-mediated co-inhibition of BRD4/MYC and FAK cooperatively induced apoptosis in TNBC cells and reduced in vivo tumour growth in the TNBC syngeneic model 4T1." (PMID 35267409, 2022). "SHK is a phosphatase inhibitor that interferes with cellular signaling mediated by TNF-α and NF-κB, and JQ1 is a first-in-class potent and selective inhibitor of the Bromodomain-containing protein 4 (BRD4) signaling pathway; it is widely used for tumor biology studies." (PMID 35264972, 2022). "Collectively, our study reveals a previously unrecognized regulatory mechanism elucidating that PRMT2/4-mediated arginine methylation of BRD4 directly promotes the BD1 binding to acetylated histones/chromatin and consequently regulates BRD4-mediated transcription, DNA repair, and tumor growth." (PMID 36475791, 2022). "Considering the prominent role of Brd4 in HIV-1 latency and tumor therapy and the essential role of CD8+ T cells in antiviral/antitumor immunity, it is urgent to clearly evaluate the effect of Brd4 inhibition on CD8+ T cell function and differentiation in vivo." (PMID 34512660, 2021). "Finally, we demonstrate that the synergistic cytotoxicity observed in vitro translates into anti-tumor effects in vivo, supporting the therapeutic potential of targeting CDK7 and BRD4 in combination in NB." (PMID 35198433, 2021). "ARV-825 treatment significantly reduced tumor growth without toxic side effects and downregulated the expression of BRD4 in vivo." (PMID 34733788, 2021). "MLN0128 is a second-generation TORC1/2 inhibitor that showed preclinical activity in MCC cell lines, decelerating tumor cell growth, diminishing cell proliferation, inducing apoptosis, and enhancing antitumor effect when combined with JQ1 (a bromodomain protein BRD4 inhibitor)." (PMID 34631574, 2021). "In addition, the SPOP protein plays a role as a tumor suppressor that negatively regulates the stability of multiple other oncogenic substrates in PrCa, including AR, SRC-3, c-MYC, ERG, DEK, BRD4 and Trim24." (PMID 34857003, 2021). "We further show that BRD4 phosphorylation promotes interaction with STAT3 to induce chromatin remodeling through concurrent binding to enhancers and super-enhancers, supporting a tumor-promoting transcriptional program." (PMID 34290255, 2021). "Here, we show that the mRNA expression of PCAF, BRD4, and ISX in 377 paired specimens from patients with HCC, and the adjacent normal tissues exhibited a tumor‐specific expression pattern, highly correlated with disease pathogenesis, patient survival time, progression stage, and poor prognosis." (PMID 34173348, 2021). "As compared with ALDHlowCD44high non-stem tumor cells, increased enrichments of both p65 and BRD4 on SEs in both TP63 and MET were observed in ALDHhighCD44high CSCs." (PMID 34172737, 2021). "Hence, co-targeting the BRD4 overexpressing cells with BET and PI3K /AKT/MEK/ ERK/ /mTOR inhibitors have been shown to affect cell proliferation, survival, and tumor growth significantly through activation of apoptosis compared to JQ1 alone." (PMID 33488950, 2020). "Moreover, JQ1, an inhibitor of bromodomain containing 4 (BRD4), significantly suppressed tumor growth of sunitinib-resistant RCC cells via MYC regulation." (PMID 32379831, 2020). "In addition, EIF3d, UBR5, BRD4, TRIM31 and LINC00152 are demonstrated to contribute to cell growth or tumor metastasis of GBC cells via PI3K/AKT pathway." (PMID 32333246, 2020). "The gains in BRD4 and AHNAK may have contributed to metastasis formation: BRD4, part of the Bromodomain and Extraterminal (BET) protein family, regulates tumour cell migration and invasion through transcription of AHNAK." (PMID 32392735, 2020). "We further compared genomic regions showing notable changes of H3K27ac and BRD4 enrichment between BETi-resistant cells and the matched parental non-resistant tumor cells." (PMID 32029739, 2020).
tumor (continued). "Furthermore, by Co-IP experiments, we demonstrated a direct interaction of BRD4 with phosphorylated CDK9 in EwS, as previously shown in other tumor entities." (PMID 32012890, 2020). "Collectively, these data indicate that a simultaneous inhibition of the integrin/FAK axis and BRD4 is highly effective in inducing tumor cell death and DNA damage response, but not proliferation." (PMID 32793596, 2020). "In addition, suppression of tumor cell viability by the co-inhibition of FAK and BRD4 is nearly equivalent to the targeted or chemo- therapeutic agents being employed for treatment of NSCLC." (PMID 32793596, 2020). "Similarly, depletion of BET genes prolonged the tumor-free survival of recipient mice in a MLPS model, with BRD4 knockdown reducing both incidence and burden of tumor." (PMID 30903020, 2019). "Correlation of BRD4 binding and drug-mediated displacement at RNA Pol II pause sites with gene expression revealed a differential behavior of sensitive and resistant tumor cells to I-BET and identified a BRD4 signature at promoters of sensitive coding and non-coding genes." (PMID 31266503, 2019). "The tumor-supporting role of LINC00346 could in part be explained by antagonization of miR-188-3p and derepression of BRD4 expression." (PMID 30728036, 2019). "More recently, it has been reported that BRD4 binds and recognizes specialized regions of H3K27 acetylation called “super-enhancers,” which control several lineage-specific genes and can be hijacked by tumor cells to express critical oncogenes." (PMID 31681756, 2019). "As we learn more about the mechanism of action behind the BRD4–NUT fusion protein, additional therapies could be identified and/or developed that may be efficacious in treating this highly aggressive tumor type." (PMID 30853030, 2019). "SF2523 is a dual PI3K/BRD4 inhibitor generated from the TP series, which orthogonally hit PI3K and BRD4 to block expression, activation, and stabilization of Myc, leading to reduced tumor growth and metastasis in various preclinical models." (PMID 30853982, 2019). "Importantly, we determined that BRD4 was dispensable for MYC expression in the most resistant cell lines and that MYC RNAi + BET bromodomain inhibition led to additive anti-tumor activity in the most resistant cell lines." (PMID 30846826, 2019). "Finally, in vivo administration of MZ1 rescued tumor growth in a JQ1-resistant xenograft model, reducing the expression levels of BRD4." (PMID 31470872, 2019). "PD-L1 is a direct target gene of the BET family member Brd4, and BET inhibition by JQ-1 has been found to enhance anti-tumor immunity by suppressing the PD-L1 expression on tumor cells and antigen-presenting cells but also through upregulation of NKG2D ligand MICA on tumor cells." (PMID 29593742, 2018). "Interestingly, we found that miR-3140 downregulated the BRD4-NUT fusion protein and suppressed in vitro tumor cell growth in a NMC cell line, Ty-82 cells." (PMID 29540837, 2018). "Other available BET/BRD4 inhibitor, such as AZD5153, were also shown strong anti-tumor effect." (PMID 29996811, 2018). "Hence, deeper understanding of BRD4’s immune modulatory roles in different immune contexts may be important in accurately administering BET inhibitors to patients without the risk of dampening the ongoing anti-tumor immune response." (PMID 30029633, 2018). "In the other hand, BRD2 and BRD4 proteins were found to co-occupy with H3K27M-K27ac, then logically, the BET inhibitor was also demonstrated could efficiently inhibit tumor progression." (PMID 29118968, 2017). "Additionally, ARV-771 was shown to induce BRD4 and c-MYC degradation in 22Rv1 tumour xenografts in mice, and more importantly led to tumour regression in the 22Rv1 model following daily subcutaneous dosing of 30 mg/kg." (PMID 28298557, 2017).
tumor (continued). "Likewise, a significant anti-tumor effect was also evident when MLN0128 was administered as a dual therapy along with JQ1, a BRD4 inhibitor that also targets c-Myc transcriptional amplification in MCC." (PMID 26536665, 2016). "Suppression of BRD4, either by siRNA or using JQ1, a pharmaceutical BRD4 inhibitor, reduced cell growth and induced apoptosis in HCC cell lines while also slowing HCC xenograft tumor growth in mice." (PMID 26575167, 2016). "This not only demonstrates the tissue specificity of BRD4 function, it indicates the feasibility of using BRD4 inhibitors and the ability of BRD4 to regulate target genes such as MYC will have to be evaluated in each tumor type." (PMID 25537515, 2015). "Western blotting of fresh-frozen re-grafted tumor lysates showed that JQ1 treatment did not suppress MYCN or Brd4 protein expression in the tumors, but clearly downregulated E2f1 protein expression." (PMID 25174395, 2015). "However, additional studies are necessary to further characterize the function and molecular mechanisms of BRD4 and other BET domain proteins in EMT during tumor progression and metastasis." (PMID 24840099, 2014). "By concurrently degrading BRD4 and mitigating immunosuppressive pathways, SPP-ARV-825 outperformed both free ARV-825 and non-targeted micelles, demonstrating the promise of brain-targeted polymeric micelle drugs in surmounting BBB constraints and effectively modulating the tumor microenvironment." (PMID 40284496, 2025). "Hence, this BRD4 degrader has a greater potential to target a broad range of tumor cells, including chemotherapy-resistant cells, not necessarily limited to senescent cells." (PMID 40649963, 2025). "To test our hypothesis, we verified the vulnerability of FTH1‐silenced tumor cells to JQ1, a pan‐BET inhibitor, initially identified as a BRD4 inhibitor, and then, it has been shown to inhibit multiple BET protein members due to the well‐preserved bromodomain sequence." (PMID 40652527, 2025). "Additionally, innovative codelivery approaches have been developed, such as DTX/ARV‐lip systems that coencapsulate BRD4–PROTAC ARV825 with docetaxel, demonstrating enhanced antitumor effects through dual mechanisms of protein degradation and chemotherapy with tumor inhibition rates reaching 57.4%." (PMID 41049269, 2025). "Importantly, the critical role of the axis in tumor cell proliferation, cell cycle progression, and survival, phenotypic plasticity, and chemoresistance is intrinsically tied to activation of YAP1 and the BRD4‐MYC axis." (PMID 40959971, 2025). "Of note, a dual inhibitor of bromodomain-containing protein 4 (BRD4) and PI3K-Akt-mTOR, SF2523 blocked Akt-mTOR activation and downregulated MYC and Bcl2 expression in the CS cell line SW1353 and in vivo strongly impaired its subcutaneous tumor growth in immunodeficient mice." (PMID 40004005, 2025). "In addition, BRD4 inhibitors, such as JQ1, have demonstrated success in targeting MYC-regulated super-enhancer networks in RMS, thereby disrupting transcriptional drivers of tumor proliferation." (PMID 40821216, 2025). "The phytochemical selectively upregulated tumor suppressor miRNAs, including miR-16-5p, miR-34a-5p, and miR-200a-5p in PC3 and LNCaP cells, suggesting potential involvement of pathways such as AKT3, TGF-β, and BRD4-mediated androgen receptor signaling in its mechanism of action." (PMID 41465187, 2025). "In addition, BD-9136 demonstrated efficient and specific reduction of BRD4 proteins within the tumor tissues of mice while exhibiting no significant impact on BRD2 and BRD3." (PMID 38389844, 2024). "Additionally, by targeting CAFs with PFD, the fibrous matrix in the tumor environment was disrupted, and the sensitivity of JQ1, a chemotherapy drug, was increased by modulating the impact of CAFs on BRD4, thereby enhancing the therapeutic effect of subsequent chemotherapy drugs." (PMID 37968249, 2024).